MTUS1 (microtubule associated scaffold protein 1)
Diseases named in the same sentence as MTUS1 in open-access papers (continued):
Sharing a sentence is not in itself a finding about the gene and the disease.
cervical cancer (1 paper, 2025). A primary or metastatic malignant neoplasm involving the cervix. "Literature evidence supports their biological relevance: CXCL14 is silenced via HPV E7-induced promoter hypermethylation, impairing immune recognition, while MTUS1 functions as a tumor suppressor and is downregulated in invasive cervical cancer." (PMID 40951335, 2025). "Another top-ranked feature, MTUS1, acts via the PTENP1/miR-19b/MTUS1 axis to suppress proliferation and invasion in cervical cancer and is often downregulated in aggressive tumors." (PMID 40951335, 2025).
Cognitive impairment (1 paper, 2020). Abnormal cognition is characterized by deficits in thinking, reasoning, or remembering. "For instance, MTUS1 expression correlated with Braak staging in AD patients and it may be associated to changes in hippocampal volume prior to onset of cognitive impairment." (PMID 32192109, 2020).
colorectal adenocarcinoma (1 paper, 2023). The most common type of colorectal carcinoma. "In conclusion, we investigated MTUS1 protein expression and evaluated the association between MTUS1 expression at the protein level and prognosis in 393 cases of colorectal adenocarcinoma." (PMID 36980447, 2023). "In the present study, we investigated MTUS1 protein expression in 393 cases of colorectal adenocarcinoma and evaluated the associations between MTUS1 protein level and clinicopathological parameters, and overall and recurrence-free survival in patients with colorectal adenocarcinoma." (PMID 36980447, 2023). "We investigated the clinicopathological significance and prognosis of MTUS1 protein expression in a large cohort of patients with colorectal adenocarcinoma by immunohistochemical staining." (PMID 36980447, 2023). "As a result, this study supports the MTUS1 protein as a tumor suppressor in colorectal adenocarcinoma." (PMID 36980447, 2023). "Recently, the relationship between reduced MTUS1 mRNA expression and poor prognosis has been reported in colorectal adenocarcinoma." (PMID 36980447, 2023). "Kaplan–Meier survival curves demonstrated a significant effect of a low MTUS1 protein level on both overall and recurrence-free survival of patients with colorectal adenocarcinoma." (PMID 36980447, 2023). "The aim of this study was to discover the prognostic significance of MTUS1 protein expression in patients with colorectal adenocarcinoma." (PMID 36980447, 2023). "In addition, the results of this study provide evidence that the immunohistochemical staining technique can be applied when MTUS1 protein is used as a biomarker for colorectal adenocarcinoma in the future." (PMID 36980447, 2023). "However, this study is the first to show that MTUS1 expression at the protein level has a significant prognostic effect in colorectal adenocarcinoma." (PMID 36980447, 2023). "Recently, the tumor suppressor function of MTUS1 has been reported at the mRNA level in colorectal adenocarcinoma; however, the correlation between MTUS1 protein level and its prognostic significance has not been reported." (PMID 36980447, 2023). "However, the clinicopathological and prognostic value of MTUS1 expression at the protein level had not been investigated in colorectal adenocarcinoma." (PMID 36980447, 2023).
congenital cardiomyopathies (1 paper, 2025). "During cardiac embryogenesis, the MTUS1 gene affects the microtubule stability and other proteins involved in adequate cell polarization, an essential process for myocardial compaction, and could therefore be associated with congenital cardiomyopathies, including LVNC." (PMID 40004439, 2025).
glomerulonephritis (1 paper, 2012). A renal disorder characterized by damage in the glomeruli. "The second major symptomatology in the MTUS1 KO mice revealed multiorgan lymphoid hyperplasia, splenomegaly, accompanied with glomerulonephritis, and sialadenitis in some animals." (PMID 22200760, 2012).
infiltrating ductal breast carcinomas (1 paper, 2009). "The expression of MTUS1 transcripts was analyzed in a series of 151 infiltrating ductal breast carcinomas and eleven normal breast tissues." (PMID 19794912, 2009).
left ventricular noncompaction (1 paper, 2025). Left ventricular noncompaction (LVNC) is a rare cardiomyopathy characterized anatomically by prominent left ventricular trabeculae and deep intratrabecular recesses causing progressive systolic and diastolic dysfunction, conduction abnormalities, and occasionally thromboembolic events. "Background/Objectives: The microtubule-associated scaffold protein 1 (MTUS1) gene affects the microtubule stability and cell polarity in the heart and could thus lead to the development of left ventricular noncompaction (LVNC)." (PMID 40004439, 2025).
metastatic cancer (1 paper, 2020). A carcinoma which has spread from the original site of growth to another anatomic site. "Knockdown of MTUS1 decreased microtubule stability, whereas increased microtubule dynamics by promoting the ratio of unphosphorylated KIF2CS192 adapting to high motility of metastatic cancer cells." (PMID 33311452, 2020).
steatosis (1 paper, 2021). Increased lipid within the cytoplasm of cells. "Some genes negatively associated with serum ferritin and steatosis degree, were consistently downregulated after treatment with iron or iron + palmitic acid (SLC51A, MTUS1)." (PMID 33962692, 2021).
Stomach adenocarcinoma (1 paper, 2021). "The mutation profile of MTUS1 in both cBioPortal and canSAR Black webserver revealed the association of S1259L with Stomach adenocarcinoma (STAD) and the substitution of glutamate at 960 position with Uterine corpus endometrial carcinoma (UCEC)." (PMID 34125870, 2021). "The box plot analysis revealed that, Stomach adenocarcinoma (STAD) results due to overexpression of MTUS1 whereas Uterine corpus endometrial carcinoma (UCEC) ensues due to underexpression of MTUS1." (PMID 34125870, 2021).
tongue tumors (1 paper, 2024). "The relative fluorescence intensity of subcutaneous xenograft tumors and in situ tongue tumors in the MTUS1/ATIP1 overexpression group was significantly weaker than that in the control group." (PMID 38725862, 2024). "In vivo, subcutaneous xenografts (xenograft volume and tumor weight) and in situ tongue tumors (tumor size) in MTUS1/ATIP1-overexpressed mice were significantly inhibited compared with those in control mice." (PMID 38725862, 2024).
uterine cancer (1 paper, 2021). Primary or metastatic malignant neoplasm involving the uterine corpus and/or the cervix. "For Uterine cancer, FAXDC2 and MYCL gene’s expression changed due to MTUS1 mutation." (PMID 34125870, 2021).
tumor (45 papers, 2009 to 2026). "Decreased levels of MTUS1 have been associated with poor prognosis and increased tumor aggressiveness in several cancer types." (PMID 41203700, 2025). "Microtubule-associated tumor suppressor gene (MTUS1) is an 8p22 candidate tumor suppressor gene encoding a family of angiotensin II (AT2) receptor-interacting proteins (ATIPs) such as ATIP1, ATIP2, ATIP3a, ATIP3b and ATIP48-10." (PMID 38725862, 2024). "The MTUS1 gene has transcript variants of various isoforms through alternative splicing that encode mitochondrial protein with tumor suppressor activity." (PMID 36980447, 2023). "MTUS1 protein was expressed at various grades in the cytoplasm of tumor cells showing a loss or decreased expression of MTUS1 protein." (PMID 36980447, 2023). "The frameshift insertion in MTUS1 presented a potential tumor-suppressor effect due to the mutation-dependent gene expression patterns and its protective effect on OS in variant carriers." (PMID 30416686, 2018). "Although the tumor suppressor effect of MTUS1 has been shown in multiple cancer forms, this is the first report to our knowledge correlating both MTUS1 gene expression and mutation status with overall survival." (PMID 30416686, 2018). "MTUS1 (microtubule-associated tumor suppressor 1) has been identified that can function as a tumor suppressor gene in many malignant tumors." (PMID 28364280, 2017). "MTUS1 is identified as an 8p22 candidate tumor suppressor gene encoding a family of angiotensin II (AT2) receptor-interacting proteins (ATIP)." (PMID 25885343, 2015). "This indicates that papillary tumours with retained MTUS1 expression have higher malignant potential than MTUS1-deficient tumours and that MTUS1 should be considered more as an oncogene rather than a tumour suppressor gene." (PMID 24650297, 2014). "In micropapillary tumours only positive MTUS1 expression was found, which, in this entity, cannot be responsible for decreased malignancy, as this variant is one of the most aggressive tumour types found in the bladder." (PMID 24650297, 2014). "The MTUS1 gene is located in a region (8p22) that shows frequent loss of heterozygosity (LOH) in several tumor types, including oral cancer." (PMID 19545354, 2009). "Therefore, more experiments are needed to verify the expression and related mechanisms of MTUS1 and elucidate its true associations with tumour-infiltrating immune cells." (PMID 35962436, 2022). "Down-regulation of MTUS1 is associated with tumor progression and poor outcome for the patients, suggesting that therapies designed to restore physiological levels of MTUS1 transcripts may be valuable." (PMID 34062782, 2021). "Low MTUS1 expression was significantly associated with larger tumor size (p < 0.001), worse histologic grade (p = 0.007), presence of lymphovascular invasion (p = 0.014), higher T stage (p = 0.044), higher N stage (p = 0.010), and more advanced 8th AJCC stage (p = 0.006)." (PMID 34359333, 2021). "Interestingly, a protective effect for overall survival was shown for the deleterious variant in MTUS1, suggesting that the genetic variant has a tumor-suppressor effect." (PMID 30416686, 2018). "Tumours with FGFR3 mutations showed more MTUS1 expression loss than wild type tumours." (PMID 24650297, 2014). "Furthermore, we provided evidence that the levels of immune infiltrates and diverse immune marker sets were associated with MTUS1 expression levels, which might extend the understanding of the roles of MTUS1 in tumour immunology." (PMID 35962436, 2022). "Upregulation of miR-184 contributed to CRC development by downregulating MTUS1, indicating a tumour-promoting role." (PMID 41379397, 2025). "ISM1 was selected as a negative prognosis factor in a previously published 21-gene signature related to the UM tumor microenvironment, while MTUS1 and IL12RB2 were considered as indicators of favorable prognosis." (PMID 38339073, 2024).
tumor (continued). "This in vivo report was the first to support this notion and revealed that MTUS1/ATIP1 showed promising antitumor activity, as indicated by a tumor inhibition rate up to 85.7%." (PMID 38725862, 2024). "The dysfunction or genetic abnormalities in mitochondrial tumor-suppressor proteins such as SIRT3 and MTUS1 lead to disturbances in mitochondrial energy metabolism, triggering cellular transformation and tumor development." (PMID 37627097, 2023). "A low level of MTUS1 protein significantly correlated with tumor size (p = 0.047), histological grade (p < 0.001), lymphovascular invasion (p < 0.001), perineural invasion (p = 0.047), and lymph node metastasis (p < 0.001)." (PMID 36980447, 2023). "The expression levels of mitochondria tumor-suppressor and DNA-repair proteins (PGC-1α, TFAM, OGG1, MTUS1, and SIRT3) were examined in tumor samples from patients with OSCC to determine the association of these proteins with patient outcomes." (PMID 37627097, 2023). "Logistic regression showed that the expression of MTUS1 in CRC was associated with advanced pathological stages and N stages, suggesting that MTUS1 is important for tumour invasion and lymph node metastasis." (PMID 35962436, 2022). "MTUS1 is considered a tumour suppressor and can play an important role in inhibiting cell proliferation, migration, and tumour growth." (PMID 35962436, 2022). "Nevertheless, the mRNA expression level and prognostic potential of MTUS1 in CRC remain unexplored due to its connection with tumour-infiltrating lymphocytes (TILs)." (PMID 35962436, 2022). "We found that MTUS1 expression was significantly correlated with tumour purity and the infiltration levels of CD8+ T cells and neutrophils in both COAD and READ." (PMID 35962436, 2022). "The results from the expression correlation analysis using GEPIA showed that MTUS1 expression levels in tumour tissues, especially CRC tissues, were closely related to most marker sets of immune cells, consistent with the findings of these previous studies." (PMID 35962436, 2022). "Nevertheless, further in-depth exploration is needed to understand the precise functions and mechanisms of MTUS1 in the tumour immune microenvironment." (PMID 35962436, 2022). "Although the downregulation of MTUS1 and its tumour-suppressor function have also been previously reported in CRC, the specific molecular mechanisms underlying MTUS1 expression remain to be elucidated." (PMID 35962436, 2022). "The logistic regression analysis indicated that the expression of MTUS1 was associated with N stage, TNM stage, and neoplasm type." (PMID 35962436, 2022). "First, we used the Oncomine database to analyse MTUS1 expression levels in different human tumour tissues and healthy tissues." (PMID 35962436, 2022). "to evaluate the expression of MTUS1 in tumour tissues and adjacent normal tissues using public databases such as the TIMER and Oncomine databases." (PMID 35962436, 2022). "As a tumor suppressor, the MTUS1 gene products play critical roles in various cellular mechanisms and prevent uncontrolled cell growth and proliferation." (PMID 34125870, 2021). "Microtubule-associated tumor suppressor 1 (MTUS1) is thought to be downregulated in arious human cancers, which suggests its role as a tumor suppressor." (PMID 34359333, 2021). "The mitochondrial tumor suppressor 1 (MTUS1) gene acts as a crucial tumor suppressor by inhibiting growth and proliferation of eukaryotic cells including tumor cell lines." (PMID 34125870, 2021). "A family of orthologues of yeast silent information regulator 3 (SIRT3), 4 (SIRT4) and mitochondrial tumor suppressor 1 (MTUS1) are important mitochondrial tumor suppressor genes which play an important role in the progression of multiple cancers." (PMID 26785117, 2016). "Although the tumor suppressor function of MTUS1/ATIP has been defined, its role in the initiation and progression of SACC has not been reported." (PMID 25885343, 2015).
tumor (continued). "In all micropapillary tumours (n = 10) strong positive MTUS1-expression was observed in the cytoplasm." (PMID 24650297, 2014). "Patients with MTUS1 expressing tumours also had better progression-free survival (PFS, mean survival time: 60.5 months, n = 111) compared to patients with MTUS1 expression loss (46.8 months, n = 86, p = 0.179, PFS graphs not shown)." (PMID 24650297, 2014). "MTUS1-expressing tumours showed higher tumour grade (p = 0.005, 5A) and stage (p = 0.004, 5B) as well as aberrant expression of differentiation marker CK20 (p = 0.004, 5C) and proliferation marker Ki67 (p = 0.004, 5D)." (PMID 24650297, 2014). "We therefore generated an MTUS1 KO mouse line for further investigations on cell proliferation, tumor development and cardiovascular disease." (PMID 22200760, 2012). "MTUS1 has shown not only to act as a tumor suppressor gene in a wide range of cancers but also to operate as an interaction partner of the AT2R and seems to act as an early component of the AT2R signaling pathway in growth inhibition." (PMID 22200760, 2012). "MTUS1 regulates the cell cycle by acting as a tumor suppressor and DDB1 is involved in nucleotide excision repair." (PMID 22664934, 2012). "ATIP3 belongs to a family of proteins (ATIP1 to ATIP4) encoded by alternative splicing of MTUS1, a candidate 8p22 tumor suppressor gene." (PMID 19794912, 2009). "MTUS1 immunostaining in tumor sections was scored and compared to MTUS1 mRNA expression levels according to Affymetrix probeset intensities." (PMID 19794912, 2009). "Mitochondrial tumor suppressor gene 1 (MTUS1) has been recently identified as a candidate tumor suppressor gene which resides in a genomic region (8p22) that shows frequent loss of heterozygosity (LOH) in several tumor types." (PMID 19545354, 2009). "Initially described as human mitochondrial tumor suppressor gene 1 (MTUS1), MTUS1 has not only been shown to act as a potential tumor suppressor in a variety of cancers but also to operate as an interaction partner of AT2, linking the AT2 pathway to carcinogenesis." (PMID 40358169, 2025). "ATIP3, a mitotic-spindle associated protein encoded by the alternative splicing of the MTUS1 tumor suppressor gene, has been reported to be significantly downregulated in TNBC, correlating with high tumor grade and distant metastasis." (PMID 38473804, 2024). "However, research on the subcellular localization of MTUS1/ATIP1, especially its localization and role in tumor cells, is relatively limited." (PMID 38725862, 2024). "Several studies have reported a tumor suppressor effect of MTUS1 protein in various human cancers." (PMID 36980447, 2023). "Not surprisingly, the results again validated the downregulation of MTUS1 in tumour samples." (PMID 35962436, 2022). "Therefore, MTUS1 is a meaningful diagnostic and sensitive prognostic marker for CRC and is involved in the infiltration of immune cells in the tumour microenvironment." (PMID 35962436, 2022). "Moreover, the expression of MTUS1 was associated with sex, age, pathological grade, TNM stage, CEA level, neoplasm type, and survival status." (PMID 35962436, 2022). "The expression of MTUS1 decreased in tumour grade IV compared to grades I and II." (PMID 35962436, 2022). "CRC patients with lower MTUS1 expression were strongly associated with pathological stage (stage III/IV vs. stage I/II, OR = 0.626, p = 0.004), N stage (N1/N2 vs. N0, OR = 1.67, p = 0.008), and neoplasm type (READ vs. COAD, OR = 0.699, p = 0.048)." (PMID 35962436, 2022). "MTUS1 can also become a new molecular target for tumour immunotherapy." (PMID 35962436, 2022). "In our previous work, MTUS1 frameshift insertion was associated with differences in gene expression and overall survival, and COL3A1 gene expression were shown to correlate with tumor aggressiveness." (PMID 31533654, 2019).